DENND1A (DENN domain containing 1A)
Description:
Guanine nucleotide exchange factor (GEF) regulating clathrin-mediated endocytosis through RAB35 activation. Promotes the exchange of GDP to GTP, converting inactive GDP-bound RAB35 into its active GTP-bound form. Regulates clathrin-mediated endocytosis of synaptic vesicles and mediates exit from early endosomes. Binds phosphatidylinositol-phosphates (PtdInsPs), with some preference for PtdIns(3)P (By similarity).
Synonyms: FAM31A; KIAA1608; FLJ21129
Tractability: Small molecule: a structure with a bound ligand is known. Antibody: UniProt places it where antibodies can reach, with high confidence; its Gene Ontology location is reachable by antibodies, with medium confidence. PROTAC: ubiquitination databases record sites on it; its protein half-life has been measured.
Gene: Protein-coding gene on chromosome 9 (123,379,648 to 123,930,152, reverse strand). Ensembl gene ENSG00000119522.
Subcellular location: Cytoplasmic vesicle, clathrin-coated vesicle membrane; Presynaptic cell membrane
Subcellular location (Human Protein Atlas): Cytosol; Vesicles
Pathways (Reactome):
Vesicle-mediated transport: RAB GEFs exchange GTP for GDP on RABs
Gene Ontology:
Molecular function: guanyl-nucleotide exchange factor activity; phosphatidylinositol phosphate binding; phosphatidylinositol-3-phosphate binding
Biological process: endocytosis; regulation of Rab protein signal transduction; endocytic recycling
Cellular component: clathrin-coated vesicle; presynaptic membrane; clathrin-coated vesicle membrane; cytosol
Genetic constraint (gnomAD): Loss-of-function variants: 49 observed, 104.78 expected, observed/expected ratio (o/e) 0.47, 90% interval 0.37 to 0.59. The upper end of that interval is the gene's LOEUF score, 0.59, which puts it in group 2 of 6, group 1 being the genes least tolerant of losing a copy. Missense variants: 1,232 observed, 1,327.4 expected, observed/expected ratio (o/e) 0.93, 90% interval 0.88 to 0.97. Synonymous variants: 554 observed, 546.07 expected, observed/expected ratio (o/e) 1.01, 90% interval 0.94 to 1.09.
Homologues: Orthologues: chimpanzee DENND1A (94% identical), macaque DENND1A (92% identical), pig DENND1A (92% identical), dog DENND1A (91% identical), rat Dennd1a (86% identical), guinea pig DENND1A (84% identical), mouse Dennd1a (84% identical), rabbit DENND1A (79% identical), tropical clawed frog dennd1a (63% identical), zebrafish dennd1a (39% identical), Drosophila melanogaster CG18659 (23% identical), Caenorhabditis elegans rme-4 (18% identical). Paralogues in human: DENND1B (34% identical), DENND1C (29% identical).
Diseases named in the same sentence as DENND1A in open-access papers:
DENND1A is named in the same sentence as 28 diseases in open-access papers, as found by Europe PMC text mining. Sharing a sentence is not in itself a finding about the gene and the disease. The quoted sentences say what the papers report.
polycystic ovary syndrome (19 papers, 2013 to 2023). A disorder that manifests as multiple cysts on the ovaries. "Nonetheless, these findings correlate with the role of DENND1A.V2 in the hyperandrogenemia associated with polycystic ovarian syndrome (PCOS) in women." (PMID 36430866, 2022). "Additional signals of shared selection signatures were found in RYR1, where the variant rs3786829 was associated with peanut allergy, another SNP was found in DENND1A, the variant carrying the signal (rs2479106) was associated with polycystic ovary syndrome." (PMID 36131251, 2022). "It has also been reported that DENND1A is a susceptibility gene for polycystic ovaries, which is essential for ovarian and embryonic development and can affect the reproductive process." (PMID 35741853, 2022). "Genetic variants in DENND1A have been suggested to play a role in susceptibility to polycystic ovary syndrome (PCOS), and the most common endocrine disease among premenopausal women." (PMID 33797841, 2021). "The DENND1A gene is one of the most important sites associated with polycystic ovary syndrome (PCOS)." (PMID 31941453, 2020). "The rs2479106 and rs10818854 polymorphisms in the DENND1A gene have been reported to be extensively associated with risk of polycystic ovary syndrome (PCOS)." (PMID 26757598, 2016). "Variants in DENND1A gene have been associated with polycystic ovarian syndrome in both European ancestry and Chinese women." (PMID 23966867, 2013). "Recent research has shown that DENND1A is associated with insulin resistance (IR) in women with polycystic ovarian syndrome, indicating that metabolic dysfunction may play a pathophysiologic role." (PMID 36292730, 2022). "Of these loci, DENND1A has been implicated as a driving force for PCOS hyperandrogenemia." (PMID 29670770, 2018). "DENND1A was a candidate gene of polycystic ovary syndrome (PCOS), which processed two variants, V1 (1009 AA) and V2 (559 AA), V2 mRNA and protein were overexpressed in PCOS theca cells compared to normal theca cells." (PMID 34946806, 2021). "The DENND1A locus is associated with polycystic ovary syndrome (PCOS), a disorder characterized by androgen excess." (PMID 32268539, 2020). "For instance, the gene showing the strongest and widest selection signature (i.e., DENND1A) plays a role in the development of polycystic ovaries, anovulation, and hyperandrogenism that mainly characterize the polycystic ovary endocrine syndrome." (PMID 33664777, 2021). "DENND1A.V2 thus plays a key role in hyperandrogenemia, indicating a possible biological relationship with IR." (PMID 32425888, 2020). "A previous study showed that DENND1A plays a significant role in polycystic ovary syndrome." (PMID 34869714, 2021). "Studies have shown that DENND1A is highly expressed in patients with polycystic ovary syndrome (PCOS) and plays a catalytic role in its development." (PMID 30524285, 2018).
hyperandrogenism (8 papers, 2019 to 2024). Excessive secretion of androgens from the adrenal glands or gonads. "Genotype–phenotype correlation studies in both Han Chinese and European PCOS patients demonstrated that DENND1A was a risk allele for androgen excess." (PMID 34367069, 2021). "Variants within DENND1A have also been associated with hyperandrogenism and ovulatory dysfunction." (PMID 38408933, 2024). "DENND1A is expressed in the theca cells and testes; therefore, it may be associated with hyperandrogenism by increasing androgen levels." (PMID 34869714, 2021). "So, DENND1A can be a mediator for hyperandrogenism of PCOS, and maybe through this pathway connect to hyperandrogenism, the common loop of all hypotheses of PCOS." (PMID 32133054, 2019).
Obesity (4 papers, 2015 to 2025). Accumulation of substantial excess body fat. "ADIPOQ, FTOTGFβ, and DENND1A as the main obesity- and chronic inflammation-related genes have roles in PCOS pathophysiology." (PMID 32133054, 2019).
adenoma (2 papers, 2013 to 2015). A neoplasm arising from the epithelium. "The three loci were located near the gene for a G protein–coupled receptor for luteinizing hormone and human chorionic gonadotropin (LHCGR) and within introns of the thyroid adenoma associated gene (THADA) and the DENN domain containing 1a (DENND1A) gene." (PMID 24086769, 2013).
depression (2 papers, 2021). "DENND1A SNPs are associated with depression, and the DENND1B transcript is downregulated in patients with depression." (PMID 35280519, 2021).
gastric cancer (2 papers, 2018 to 2021). A primary or metastatic malignant neoplasm involving the stomach. "This shows that the expression of DENND1A has a certain guiding significance in predicting the prognosis of patients with gastric cancer." (PMID 30524285, 2018). "We found that DENND1A is highly expressed in gastric cancer cells by screening the expression of GEFs in gastric cancer cell lines." (PMID 30524285, 2018). "Further results reveal that the higher the expression of DENND1A, the shorter progression-free survival of gastric cancer patients." (PMID 30524285, 2018). "In this study we demonstrated for the first time that EGF stimulates EGFR and activates Rab35 via DENND1A in gastric cancer cells." (PMID 30524285, 2018). "In summary, we confirmed that EGF-induced activation of Rab35 in gastric cancer cells is regulated by DENND1A in this study." (PMID 30524285, 2018). "Compared with normal gastric tissue, DENND1A showed a significant high expression in gastric cancer tissues." (PMID 30524285, 2018). "In addition, we analyzed the expression of DENND1A in gastric cancer tissues of the GEO database and found that the expression of DENND1A in gastric cancer tissues was significantly higher than that in normal gastric tissues (GES13861, n = 90, P = 0.0032)." (PMID 30524285, 2018). "Finally, we verified that DENND1A expression was significantly higher in gastric cancer tissues compared to normal gastric cancer tissues by tissue microarray staining at the tissue level." (PMID 30524285, 2018). "Moreover, the high expression of DENND1A significantly shortened the progression-free survival of patients with gastric cancer." (PMID 30524285, 2018). "At the same time, EGF-DENND1A-Rab35 signaling pathway with DENND1A as a regulatory center may also become a new target for the treatment of gastric cancer." (PMID 30524285, 2018). "These all suggest that Rab35 activated by DENND1A may play an important role in the development of gastric cancer." (PMID 30524285, 2018). "Ultimately, the expression level of DENND1A predicts the survival status of gastric cancer patients and may become one of the important targets for the treatment of gastric cancer." (PMID 30524285, 2018). "In view of this, our studies in gastric cancer have shown that DENND1A exerts GEF action during the activation of Rab35 stimulated by EGF, and through its interaction with Grb2, it can regionally recruit activated Rab35 and then promote the migration of tumor cells." (PMID 30524285, 2018). "Further analysis based on database data showed that the higher expression of DENND1A, the shorter progression-free survival of gastric cancer patients, which indicated that the prognosis of gastric cancer patients with high DENND1A expression is worse (GES26253, n = 190, 242, P = 0.0125)." (PMID 30524285, 2018). "Additionally, DENND1A was also related to gastric cancer, endometrial carcinoma." (PMID 34946806, 2021). "In the process of gastric cancer cell migration, EGF activates EGFR, which through the combination of Grb2 and DENND1A plays a role in target molecule activation and targeted recruitment." (PMID 30524285, 2018).
Hirsutism (2 papers, 2013 to 2020). Abnormally increased hair growth referring to a male pattern of body hair (androgenic hair). "In European patients, one mistyped SNP (rs189947178, A/C) that may alter the structural conformation of the DENND1A protein is more prevalent in PCOS patients with moderate hirsutism." (PMID 31941453, 2020).
Insulin resistance (2 papers, 2020 to 2022). Increased resistance towards insulin, that is, diminished effectiveness of insulin in reducing blood glucose levels. "PCOS susceptibility variants in THADA and INSR are associated with metabolic syndrome and variants in TOX3 and DENND1A are associated with insulin resistance." (PMID 32425888, 2020). "This genotype-phenotype study provides clues that THADA, INSR, TOX3, and DENND1A play important role in the etiology of PCOS, possibly through insulin resistance and metabolic disorder related pathways." (PMID 32425888, 2020).
cervical dystonia (1 paper, 2021). "For example, SNPs in COL8A1, DENND1A, and GABBR2 were found to be associated with cervical dystonia in a multicenter GWAS." (PMID 35273550, 2021).
lung carcinoma (1 paper, 2012). "MiR-601, located within DENND1A gene which up-regulated in uterine cervical cancer, could affect nuclear factor-kappa B signaling pathways in human lung cancer cells A549." (PMID 22970209, 2012).
major depressive episode (1 paper, 2023). "Differential expression of DENND1A has been observed in patients with major depressive episodes." (PMID 37679827, 2023).
migraine (1 paper, 2022). "Of the protein-coding genes near the novel lead SNPs from analysis of migraine and T2D, L3MBTL2 and DENND1A are also particularly interesting." (PMID 36292730, 2022).
Ovarian Hyperandrogenism (1 paper, 2022). Increased production of androgens by the ovaries. "But without evidence of GWAS-identified, PCOS-associated, intronic gene variants of DENND1A enabling DENND1a.v2 over-expression or ovarian hyperandrogenism, investigations continue into the pathogenic mechanisms underlying this PCOS-associated gene variant." (PMID 35012577, 2022).
metabolic disorder (1 paper, 2020). "This genotype-phenotype study thus provides clues that THADA, INSR, TOX3, and DENND1A play a role in PCOS possibly through a metabolic disorder-related pathway." (PMID 32425888, 2020). "It suggests that THADA, INSR, TOX3, and DENND1A might play a role in PCOS through a metabolic disorder related pathway." (PMID 32425888, 2020).
DENND1A also shares sentences with these, for which no sentence is quoted: diabetes (2 papers); Stroke (2); anovulation (1); blood tumors (1); bovine tuberculosis (1); diffuse large B-cell lymphoma (1); endocrine disease (1); endometrial carcinoma (1); metabolic syndrome (1); peanut allergy (1); psychiatric disorder (1); rhabdoid tumor (1); tumor (1); type 2 diabetes mellitus (1).